REM2 (RRAD and GEM like GTPase 2)
Description:
Binds GTP saturably and exhibits a low intrinsic rate of GTP hydrolysis.
Synonyms: FLJ38964
Tractability: Small molecule: a structure with a bound ligand is known. Antibody: UniProt places it where antibodies can reach, with medium confidence; its Gene Ontology location is reachable by antibodies, with medium confidence. PROTAC: its protein half-life has been measured.
Gene: Protein-coding gene on chromosome 14 (22,883,136 to 22,887,686, forward strand). Ensembl gene ENSG00000139890.
Subcellular location: Cell membrane
Gene Ontology:
Molecular function: protein binding; calcium channel regulator activity; GTP binding; GTPase activity
Cellular component: plasma membrane
Genetic constraint (gnomAD): Loss-of-function variants: 24 observed, 21.37 expected, observed/expected ratio (o/e) 1.12, 90% interval 0.81 to 1.58. The upper end of that interval is the gene's LOEUF score, 1.58, which puts it in group 6 of 6, group 1 being the genes least tolerant of losing a copy. Missense variants: 425 observed, 425.24 expected, observed/expected ratio (o/e) 1, 90% interval 0.92 to 1.08. Synonymous variants: 185 observed, 176.77 expected, observed/expected ratio (o/e) 1.05, 90% interval 0.93 to 1.18.
Homologues: Orthologues: chimpanzee REM2 (99% identical), macaque REM2 (98% identical), pig REM2 (94% identical), mouse Rem2 (93% identical), rat Rem2 (93% identical), guinea pig REM2 (90% identical), tropical clawed frog rem2 (53% identical), zebrafish rem2 (35% identical). Paralogues in human: RRAD (41% identical), GEM (38% identical), REM1 (36% identical), RIT1 (21% identical), RASL12 (20% identical), RIT2 (19% identical), RALB (18% identical), RRAS2 (18% identical), RALA (18% identical), RAP2A (18% identical), MRAS (18% identical), RASL11B (18% identical), and 23 more.
Diseases named in the same sentence as REM2 in open-access papers:
REM2 is named in the same sentence as 8 diseases in open-access papers, as found by Europe PMC text mining. Sharing a sentence is not in itself a finding about the gene and the disease. The quoted sentences say what the papers report.
ciliopathies (1 paper, 2020). "It contains several proteins, such as INTU, FUZ, WDPCP, JBTS17 and RSG1 (REM2- and RAB-like small GTPase 1), whose genes are mutated in ciliopathies." (PMID 31562761, 2020).
Huntington disease (1 paper, 2024). Huntington disease (HD) is a rare neurodegenerative disorder of the central nervous system characterized by unwanted choreatic movements, behavioral and psychiatric disturbances and dementia. "Rad And Gem-Like GTP-Binding Protein 2 (Rem2), a member of the RGK family of Ras-like GTPases, is implicated in Huntington’s disease and Long QT Syndrome and is highly expressed in the brain and endocrine cells." (PMID 38978817, 2024).
insulinoma (1 paper, 2021). "Importantly, the RGKs expression is activity-dependent as it has been shown that high electrical activity in response to elevated glucose levels strongly induced Rem2 expression in the mouse insulinoma MIN6 cell line, while in neurons, KCl treatment upregulates Rem2 and Gem mRNA levels." (PMID 34440773, 2021).
Timothy syndrome (1 paper, 2024). "While mutations in certain regions of Rem2 may be linked to human disorders such as Timothy Syndrome, some mutations remain unattributed to any specific condition or any observed phenotypic differences." (PMID 38978817, 2024). "Studies have shown that the Rem2 protein can interact with CACNA1C and modulate its activity, suggesting that the Rem2 gene may be involved in the pathogenesis of Timothy syndrome." (PMID 38978817, 2024).
infection (1 paper, 2018). The state of being infected such as from the introduction of a foreign agent such as serum, vaccine, antigenic substance or organism. "Acute cortical slices were then isolated either 4 days post infection (4 d.p.i.) or 10–12 d.p.i., and f-I curves constructed from GFP+, layer 2/3 pyramidal neurons to determine if Rem2 regulates neuronal intrinsic excitability in a cell-autonomous manner." (PMID 29809135, 2018).
REM2 also shares sentences with these, for which no sentence is quoted: co-infection (2 papers); tumor (2); Long QT Syndrome (1).